PCK1 (phosphoenolpyruvate carboxykinase 1)
Diseases named in the same sentence as PCK1 in open-access papers (continued):
Sharing a sentence is not in itself a finding about the gene and the disease.
melanoma (continued). "Moreover, PCK1 overexpression contributes to melanoma tumorigenesis and drug resistance, whereas its knockdown inhibits TRCs’ proliferation and tumorigenesis capacity." (PMID 40565936, 2025). "Collectively, targeting PCK1 upregulation in TRCs derived from melanoma may be a promising anti-tumor strategy." (PMID 37250903, 2023). "PCK1 was a highly expressed protein in drug-resistant melanoma cells." (PMID 36700470, 2022). "However, when 3-MPA was used to inhibit PCK1, KEAP1 was activated leading to ROS accumulated, which caused oxidative attack to resistant melanoma cells." (PMID 36700470, 2022). "In one study, PCK1 was found to enhance melanoma tumor re-initiation." (PMID 31841108, 2019). "However, elevated PCK1 expression has also been found in other types of cancers, such as melanoma, breast cancer, and colorectal cancer, where it supports anabolic pathways and cell proliferation." (PMID 30619751, 2018). "Furthermore, glycolysis metabolite PEP may be a metabolic checkpoint for anti-tumor T-cell responses, and PEP carboxykinase 1 (PCK1) overexpressed T cells can limit tumor growth and prolong the survival time of melanoma mice." (PMID 39588377, 2024). "Additionally, PCK1 is involved in developing melanoma drug resistance." (PMID 39578429, 2024). "PCK1 inhibition could block the growth of TRCs and impair the development of melanoma." (PMID 37250903, 2023). "TRCs derived from melanoma could alter glucose metabolism by hijacking PCK1." (PMID 37250903, 2023). "Combined with the western blot results, these results suggested that CD271 and SOX10, which have been recognized as indicators of melanoma stemness, were highly expressed in A2058R and OE cells, indicating that PCK1 could modify cancer stemness in the development of drug resistance." (PMID 36700470, 2022). "3-MPA, a known inhibitor of gluconeogenesis, can inhibit PCK1 selectively, and shows a good performance in antitumor activity.However, the mechanism of PCK1 in melanoma remains unknown and regulation of metabolic reprogramming may be an Achilles’ heel of chemoresistance." (PMID 36700470, 2022). "Therefore, the results indicated that PCK1 was a crucial molecule that could enhance the tolerance of melanoma cells to vemurafenib." (PMID 36700470, 2022). "Upregulation of PCK1 expression is a key metabolic feature of tumorigenic TRCS, thus providing a potential target for melanoma therapy." (PMID 39578429, 2024). "T cells that overexpress phosphoenolpyruvate carboxykinase 1 (PCK1) increase PEP production, limit tumor growth, and prolong the survival of melanoma mice." (PMID 38139250, 2023). "This required the presence of PCK1 to synthesize abundant reductive NADPH via the PPP, and its inhibition impeded the growth of melanoma." (PMID 36700470, 2022). "PEP supplementation or overexpression of PhosphoEnolPyruvate CarboxyKinase 1 (PEPCK1) in CD4+ T cells boosted IFNγ production and antitumor function in a melanoma mouse model." (PMID 29966302, 2018). "The role of PCK1 in non-gluconeogenesis in melanoma provides new hope for its treatment and has become a key metabolic target for melanoma treatment." (PMID 39578429, 2024). "Meanwhile, in this experiment, PCK1 could not alter the EMT of melanoma for achievement of drug resistance." (PMID 36700470, 2022). "In contrast, PCK1 is upregulated and oncogenic in tumors originating from non-gluconeogenic organs (CRC, lung cancer, melanoma, breast cancer, pancreatic cancer, and gastric cancer)." (PMID 39578429, 2024).
liver cancer (17 papers, 2017 to 2025). An epithelial or non-epithelial malignant neoplasm that arises from the liver. "In addition, targeting GFPT1 by DON blocked the PCK1-loss induced O-GlcNAclyation and liver cancer aggressiveness, and enhanced anti-PD-1 immunotherapy effects in pancreatic cancer." (PMID 36158580, 2022). "Therefore, to investigate the correlation between each NFYA variant and PCK1 in 297 liver cancers using RNA-seq data from TCGA, we classified by the logFC of VIM/CDH1 into two groups: those predominantly expressing NFYAv1 (1 < logFC) and those predominantly expressing NFYAv2 (logFC < −1)." (PMID 36092708, 2022). "The role of PCK1 as a protein kinase regulating lipogenesis has been demonstrated in liver cancer, non-small cell lung cancer (NSCLC), and esophageal cancer." (PMID 39578429, 2024). "Recently, studies have disclosed that PCK1 is involved in regulating epigenetic modifications to affect the progression of liver cancer." (PMID 39578429, 2024). "In particular, the levels of the rate-limiting enzyme phosphoenolpyruvate carboxykinase 1 (PCK1) are decreased in liver cancer." (PMID 37108625, 2023). "We aimed to understand the molecular mechanisms underlying the positive correlation between H3K9me3 and the metabolic enzyme PCK1 during liver cancer development." (PMID 37166978, 2023). "The mRNA expression of GCGR, G6PC, FBP1, and PCK1 are decreased in patient tumors and heavily silenced in many established liver cancer cell lines." (PMID 35123542, 2022). "Studies have shown that the expression level of PCK1 in liver cancer specimens and liver cancer cells is lower than that in normal samples." (PMID 34957118, 2021). "Acute suppression of autophagy with lysosome inhibitors (Chloroquine or Bafilomycin A1) in statin treated human liver cancer cell line (HepG2 cells) has thus been shown to reduce mRNA levels of the two gluconeogenic enzymes g6pc and pck1." (PMID 30936838, 2019). "Overexpression of PCK1 can reduce the survival rate of liver cancer cell lines, induce apoptosis, inhibit cell migration, and activate the expression of PCK1 and thus may be potentially utilized as a therapeutic strategy for liver cancer (Liu MX." (PMID 34957118, 2021). "Additionally, sustained activation of protein kinase B in liver cancer phosphorylates phosphoenolpyruvate carboxykinase 1 (PCK1) in the cytoplasm, and phosphorylated PCK1 promotes SREBP-1 to leave the endoplasmic reticulum and activate SREBP-1, thereby promoting tumor growth." (PMID 37497413, 2023). "To further confirm that PCK1 exerted antitumor effects through S100A11 suppression via upregulation of H3K9me3 modification in vivo, we developed a DEN/CCl4/PB-induced mouse model of liver cancer." (PMID 37166978, 2023). "Additionally, SIRT2 increases the activity of Phosphoenolpyruvate Carboxykinase 1 (PEPCK1) and Glutaminase (GLS), which promote the metabolism of glycolysis and inhibit the E-cadherin pathway, which promotes the invasion of liver cancer cells." (PMID 36750593, 2023).
colon carcinoma (16 papers, 2017 to 2024). "C4 spots expressed high levels of mitochondrial phosphoenolpyruvate carboxykinase 1 (PCK1) gene, which increases colon cancer cell growth in part by promoting the consumption of both glucose and glutamine in the tricarboxylic acid (TCA) cycle." (PMID 38729966, 2024). "13C tracing has revealed that the PCK1 inhibitor reduced the incorporation of lactate into the TCA cycle in colon tumor cells." (PMID 37250903, 2023). "Based on these results, PCK1 functions as a metabolic link to support colon cancer cell proliferation." (PMID 37250903, 2023). "In colon tumors, PCK1 has been found to enhance glucose and glutamine consumption toward anabolic metabolism to promote colon tumor cell proliferation." (PMID 37250903, 2023). "Recently, we showed that the metabolic enzyme phosphoenolpyruvate carboxykinase (PEPCK; HUGO: PCK1) increases colon cancer cell growth in part by promoting the use of both glucose and glutamine by the TCA cycle." (PMID 31388420, 2019). "Five genes (FAS, VWA5A, SPTBN2, PCK1, and TIMP1) significantly affect the prognosis of patients with colon cancer." (PMID 34957118, 2021). "Inhibition of cancer growth by inhibition of PCK1 or PCK2 has been shown in different tumor models in vivo, including xenografts of lung cancer, prostate cancer and colon cancer." (PMID 33540663, 2021). "A dual PCK1 and PCK2 inhibitor that was efficient in reducing subcutaneous colon cancer growth in vivo was recently found to be well-tolerated without inducing weight loss, albeit slightly reducing basal glucose levels in starved mice." (PMID 33540663, 2021). "Finally, the ARGPI was constructed based on five apoptosis genes (FAS, VWA5A, SPTBN2, PCK1, and TIMP1), which can effectively improve the prediction of colon cancer progression." (PMID 34957118, 2021).
Hepatic steatosis (15 papers, 2017 to 2026). Steatosis is a term used to denote lipid accumulation within hepatocytes. "PCK1, an enzyme involved in glucose production, also regulates adipogenesis and is associated with hepatic steatosis." (PMID 38319729, 2024). "Adeno-associated virus forced expression of hepatic PCK1 improves metabolic-associated fatty liver disease in male mice." (PMID 39578429, 2024). "Phosphoenolpyruvate carboxykinase 1 (Pck1) is an enzyme involved in glucose production that also regulates lipogenesis and has been linked to liver steatosis." (PMID 36918564, 2023). "Consequently, PCK1 deficiency stimulates lipid gene expression and lipid synthesis, leading to metabolic-associated fatty liver disease." (PMID 39578429, 2024). "Hepatic PCK1 deficiency may be important in hepatic steatosis and fibrosis development through paracrine secretion of PDGF-AA in male mice, highlighting a potential therapeutic strategy for MAFLD." (PMID 36918564, 2023). "Studies have reported that PCK1 causes liver metabolic disorders via the PI3K/AKT/PDGF axis, ultimately leading to fatty liver disease." (PMID 41546098, 2026). "Whereas Pck1, which was downregulated in thymectomized mice has been demonstrated to be protective of diet induced hepatic steatosis." (PMID 41034932, 2025). "The upregulated PPARα involved in mitochondrial biogenesis and ketogenesis, specifically through the action of phosphoenolpyruvate carboxykinase 1 (PCK1), which reduced hepatic triglycerides and overall liver steatosis." (PMID 40221799, 2025). "We identified a robust decrease in PCK1 expression in the livers of MAFLD mice and patients with NAFLD/NASH, causing severe hepatic steatosis and confirming that disordered hepatic gluconeogenesis affects lipid homeostasis." (PMID 36918564, 2023). "In the present study, liver-specific Pck1 knockout induced significant hepatic steatosis even under normal feeding conditions." (PMID 36918564, 2023). "In summary, hepatic Pck1 depletion showed substantial liver steatosis, inflammation and fibrosis in PTEN-null livers." (PMID 36918564, 2023). "Intriguingly, it has been shown that mice with a liver-specific knockout of Pck1 develop hepatic steatosis, whereas Pck1 overexpression in skeletal muscle reduced weight gain and had a positive effect on metabolism and energy in mice." (PMID 31645433, 2019). "To elucidate the mechanisms by which PUR effectively ameliorated hepatic steatosis in diabetic rats, we first assayed the gene expression of the key enzyme in gluconeogenesis such as Pck1 and G6p." (PMID 30057680, 2018). "In patients with fatty liver, the mRNA level of PCK1 is reduced." (PMID 41546098, 2026). "Moreover, the deletion of PCK1 significantly exacerbated hepatic steatosis, fibrosis, and inflammation in mouse models fed the HFCD-HF/G." (PMID 36918564, 2023). "Hepatic steatosis is found in as many as 75% of individuals with T2DM, and our studies suggest that glycerol inhibition of Pck1 might contribute to the development of fatty liver." (PMID 31645433, 2019). "Pck1, a gene that may protect against hepatic steatosis was downregulated in thymectomized mice." (PMID 41034932, 2025). "Among that, PCK1-mediated phosphorylation of INSIG1/2 could promote the activation of SREBP1 lipogenesis, and AQP9 could facilitate the hepatic uptake of glycerol and knockdown of the AQP9, thereby reducing hepatic steatosis." (PMID 38665091, 2024).
metabolic syndrome (15 papers, 2017 to 2025). A cluster of metabolic risk factors for CARDIOVASCULAR DISEASES and TYPE 2 DIABETES MELLITUS. "Slc7a8, Pck1, Mgll, and Bhmt are associated with the regulation of metabolic homeostasis in the treatment of metabolic syndrome, and Fkbp5 plays a crucial role in the inflammatory response." (PMID 39126116, 2024). "Conversely, miR-29 suppresses PCK1 by targeting its 3’ untranslated region (UTR) for mRNA degradation, impairing gluconeogenic capacity—a mechanism implicated in metabolic syndrome pathogenesis where miR-29 overexpression correlates with insulin resistance." (PMID 40998906, 2025). "The up-regulated proteins of PCK1 indicate that the glucose metabolism is also involved in dyslipidemia." (PMID 36234935, 2022). "Other studies have found that PCK1 gene silencing can improve glycemic control, insulin sensitivity, and aberrant dyslipidemia in Leprdb/J mice." (PMID 31805072, 2019). "This, together with the sharply increased expression of phosphoenolpyruvate carboxykinase (pck1) only under Li-PIC3+HFD conditions, suggests a deregulation of glucose metabolism mirroring aspects of human metabolic syndrome." (PMID 35203687, 2022). "Pck1 is a gluconeogenic enzyme in the PPAR pathway and holds a well-established role in gluconeogenesis within the liver and kidney, which influences fat production and metabolism and thus is involved in metabolic syndrome." (PMID 39126116, 2024).
colorectal cancer (13 papers, 2017 to 2024). A primary or metastatic malignant neoplasm that affects the colon or rectum. "PCK1 also increases nucleotide synthesis and thus promotes proliferation in colorectal cancer cells, providing another possible mechanism for PCK1 mediated β-cell proliferation." (PMID 36455788, 2022). "Taken together, these results indicate that PCK1 promotes colorectal cancer liver colonization and represents a potential therapeutic target in the prevention of CRC at risk for metastatic disease." (PMID 31841108, 2019). "Furthermore, under hypoxic conditions, PCK1 has been shown to support pyrimidine nucleotide biosynthesis, which is crucial for the metastatic growth of colorectal cancer." (PMID 38670942, 2024). "In this study, we aimed to determine the functions of PCK1 in colorectal cancer (CRC)." (PMID 37062825, 2023). "In addition, a recent report showed that PCK1 drove liver metastasis of colorectal cancer by promoting nucleotide synthesis under hypoxia." (PMID 34650217, 2021). "Metastasizing colorectal cancer cells depend on PCK1 and the nucleotide-synthesizing enzyme to grow, so therapies that target these proteins may help more patients to survive this kind of cancer." (PMID 31841108, 2019). "PCK1 and EFNA1 have been found to be involved in important life activities such as cell proliferation and apoptosis, tumor angiogenesis, malignant cell events, and invasiveness, and their expression is upregulated in a variety of tumors [such as colorectal cancer]." (PMID 35910380, 2022).
breast carcinoma (7 papers, 2018 to 2024). "These targeted miRNAs are important regulators involved in the development and metastasis of breast cancer that are mainly associated with the change in expression of PCK1 and LPL." (PMID 38791477, 2024). "Over-expression of the precursor of hsa-miR-10b-5p is directed towards the downregulation of PCK1, activating glycolysis over gluconeogenesis; enhancing the Warburg effect, a metabolic hallmark of cancer cells; and facilitating the metastasis of breast cancer cells." (PMID 38791477, 2024). "Since PCK1 performs an anti-oncogenic role in gluconeogenic organisms, its gains in CNVs would thus affect breast cancer metastasis in the liver due to its tumor-promoting role." (PMID 38791477, 2024). "Studies have shown that Sp1 can directly bind to the promoter region of the PCK1 and controls the proliferation of breast cancer cells by interacting with insulin-like growth factors I receptor, enhancing their transcriptional activity." (PMID 38791477, 2024). "PCK1 expression allows breast cancer cells that have metastasized to the liver to create a disadvantage, driving key metabolic fluxes." (PMID 38791477, 2024). "PCK1, LPL, and SFRP2 play a role in breast cancer’s initial and developmental stages, and KRT6B is exclusively related to the developmental stages." (PMID 38791477, 2024). "This study’s integrative approach unveiled metabolic reprogramming, suggesting altered PCK1 and LPL expression as key in breast cancer metastasis recurrence." (PMID 38791477, 2024).
Glucose intolerance (7 papers, 2005 to 2023). Glucose intolerance (GI) can be defined as dysglycemia that comprises both prediabetes and diabetes. "The expression of gluconeogenic genes, including Pck1 and G6pc, was upregulated in the liver of iAsF1-F mice vs. conF1-F mice in the refed condition, which was consistent with the glucose intolerance." (PMID 37691128, 2023). "Dysregulation of glyceroneogenesis in WAT induced by Pck1 mutation resulted in elevated TG levels in liver, impaired WAT glucose uptake and global glucose intolerance, a similar metabolic phenotype as seen in high dose NR-treated mice in our study." (PMID 31614949, 2019). "The liver-specific STAT3 knockout mouse is insulin resistant and develops glucose intolerance when fed a high-fat diet, due in part to increased expression of PCK1 and G6P." (PMID 15985155, 2005). "The glucose intolerance that resulted from arsenic exposure led to glucose accumulation in the circulation and limited gluconeogenesis, which can explain why we observed a down-regulation of PCK1 under arsenic exposure." (PMID 37888683, 2023). "Estrogen treatment represses hepatic glucose production, downregulates the hepatic expression of G6pc and Pck1, and rescues OVX-induced glucose intolerance." (PMID 37691128, 2023). "Adenoviral mediated reconstitution of STAT3 signaling ameliorated glucose intolerance in both L-ST3KO and Lepr-/- mice by lowering PCK1 and G6P levels, demonstrating the importance of STAT3 signalling to hepatic glucose output." (PMID 15985155, 2005).